INS (insulin)
Diseases named in the same sentence as INS in open-access papers (continued):
Sharing a sentence is not in itself a finding about the gene and the disease.
tumor (continued). "Metformin, used as a first-line medicine in the treatment of DM, has a direct anticancer impact on a wide variety of tumor cells, including tumor stem cells, in both insulin-dependent and insulin-independent models." (PMID 38020199, 2023). "We previously showed that RasV12, dlg1RNAi eye imaginal disc tumours express elevated levels of the dIlp antagonist ImpL2, consequently leading to a reduction in fat body insulin signalling." (PMID 38014610, 2023). "In particular, the most important role in tumorigenesis is played by adipokines, which can affect tumour biology by regulating insulin resistance and inflammation." (PMID 37238992, 2023). "The primary mechanism underlying the reliance of metformin on insulin involves reduction in insulin levels, which leads to diminished insulin binding to the insulin receptor (IR), thereby impeding tumor growth." (PMID 37835462, 2023). "In this study, we have unveiled that SGLT2 inhibitors exhibit the capacity to notably reduce 18F-FDG uptake in skeletal muscle compared with that of insulin under hyperglycemic condition, and enhance the tumor-to-skeletal muscle contrast." (PMID 37884546, 2023). "Supporting the association between nutritional restriction and REPTOR expression, systemic reduction of insulin signaling in a tumor-free setting through ectopic expression of ImpL2 in normal guts, also led to an upregulation of REPTOR in thoraces." (PMID 37582831, 2023). "Insulin, a signaling molecule that controls systemic metabolic homeostasis, can be seen as enabling tumor development by providing a mechanism for PI3K activation and enhanced glucose uptake, and plays a role in cytotoxic therapy response." (PMID 36775056, 2023). "The effect of PTEN loss on cellular metabolism is also complex, ultimately leading to improved insulin sensitivity, providing a survival advantage for tumor cells through an improved ability to handle metabolic stress." (PMID 37109525, 2023). "Among these KEGG pathways, tumor-related pathways included ubiquitin-mediated proteolysis, insulin signaling pathway, cell cycle, regulation of autophagy, mTOR signaling pathway, ERBB signaling pathway, WNT signaling pathway, and Notch signaling pathway." (PMID 36900050, 2023). "Intraoperative insulin measurements showed a rapid decline in serum insulin levels after the resection, indicating successful removal of the tumor." (PMID 37563593, 2023). "The remaining three RenNETs with hormonal syndrome included an insulin-secreting tumor with a hypoglycemic syndrome, a glucagon-producing tumor with a glucagonoma-like syndrome, and a tumor with a carcinoid-like syndrome." (PMID 37405461, 2023). "Evidence from preclinical studies is most supportive of tumor-modulating roles for insulin, CCK, and Lcn2, whereas data are less conclusive for the adipokines leptin and adiponectin, despite correlations from human epidemiologic studies." (PMID 37648285, 2023). "Previous studies have shown that metastatic insulinoma has a longer duration of symptoms, higher insulin and C-peptide levels, and a larger tumor size." (PMID 37251916, 2023). "Our results place REPTOR under the control of ImpL2, a secreted factor from gut yki-tumors that reduces systemic insulin signaling." (PMID 37582831, 2023). "The endocrine functions attributed to myokines regulate body weight, low-grade inflammation, insulin sensitivity, tumor growth suppression, and cognitive function improvement." (PMID 38203683, 2023). "This was in regard to the fact that Walker 256 tumor cells were easily transplanted into rats and obese rats with Walker 256 tumor had lower insulin circulation than tumor-free obese rats." (PMID 36678826, 2023).
tumor (continued). "In these cachexia models, the expression of ImpL2, the Drosophila homolog of mammalian IGFBP, is increased in tumor tissues, which disrupts both insulin and IGF-1 signaling." (PMID 35388147, 2022). "APN exerts its effects on tumor tissues influencing multiple intracellular cascades as well as by modulating tumor angiogenesis, inflammation and insulin sensitivity." (PMID 35162142, 2022). "MMes, driven by saturated fatty acids (e.g. palmitate) released by insulin-resistant adipocytes, accumulate in mammary fat of obese mice and humans and promote stemness within the tumour via IL-6." (PMID 36038791, 2022). "Similar to our previous study, the pancreatic area covered by PanIN and tumor in the PK-Ins1-/-;Ins2+/+ control mice was approximately twice that of the PK-Ins1-/-;Ins2+/- experimental mice with reduced insulin levels (filled circles indicated mice with PDAC)." (PMID 35189981, 2022). "Insulin also inhibits sex hormone-binding globulin levels, leading to higher levels of biologically active estrogens, which in turn can induce tumor cell proliferation and inhibit apoptosis." (PMID 36040641, 2022). "In this review, we describe the proposed mechanisms of insulin-lowering diets in countering tumor progression and present preclinical evidence supporting further clinical studies of insulin-lowering diets to reduce metastatic disease burden." (PMID 36079800, 2022). "Insulin also conducts lipid metabolic reprogram, which manifests as an increased lipid synthesis rate in tumor cells." (PMID 35252207, 2022). "Preclinical results suggest that enhanced tumor immunity and decreased growth signaling, via lowering of circulating insulin and insulin growth factor 1 (IGF-1) levels form the potential underlying mechanisms." (PMID 35326541, 2022). "Insulin directly promotes breast tissue and tumor cell proliferation, thus possibly promoting BC incidence." (PMID 36686748, 2022). "It is believed to play a role in several malignancies through various mechanisms, among which are the regulation of cytokines and hormone release, insulin-resistance, and tumor cell proliferation." (PMID 35328248, 2022). "Peroxisome proliferator‐activated receptors (PPARs) are nuclear transcription factors that are related to cellular growth and differentiation, energy metabolism, insulin sensitization, and tumor regulation." (PMID 35023304, 2022). "In other mice studies, hepatocellular carcinoma tumor burden positively correlated with hepatic fat accumulation and insulin and liver IL-6 levels and inversely correlated with adiponectin levels." (PMID 35745105, 2022). "Insulin can combine with the insulin receptor on the surface of tumor cells to promote the mitosis of tumor cells." (PMID 36199796, 2022). "Insulin is secreted by beta cells in the pancreatic islet and is recognized by IRs, which are expressed in all cell types in the body, including tumor cells." (PMID 35244142, 2022). "Although these mechanisms are systemic changes to metabolism that occur through insulin signaling, changes in macronutrient intake involving the type of carbohydrate ingested can also have direct effects on tumor cell central carbon metabolism." (PMID 36062923, 2022). "In contrast, the islets of Langerhans situated within the structurally altered non-tumor bearing KPC7−/− pancreas had a drastically reduced percentage of insulin expressing cells." (PMID 35372352, 2022). "Nevertheless, circulating insulin still significantly correlated with PanIN plus tumor area in female mice, confirming our previous report with another insulin gene dosage configuration." (PMID 35189981, 2022). "Noteworthy, besides the metabolic effect, insulin plays an important role in the regulation of cell growth and exerts a mitogenic effect on tumor development." (PMID 35933633, 2022).
tumor (continued). "In a study, large, medium and small doses of insulin combined with 5-Fu were found to be significantly more effective than 5-Fu alone in suppressing tumour growth in nude mouse S180 sarcoma and H22 liver cancer xenograft models." (PMID 36776356, 2022). "Here, we developed a combined strategy using radiosensitizer gold nanoparticles coated with insulin to cross the blood-brain barrier and shuttle tumor-targeting antibodies (cetuximab) into the brain." (PMID 36324626, 2022). "AKT1, for instance, plays a key role in regulating cell survival, insulin signaling, angiogenesis, and tumor formation." (PMID 36339598, 2022). "Because the patient’s glycemic control rapidly worsened in synchrony with the tumor growth, insulin therapy was initiated." (PMID 36576596, 2022). "Reduction of tumor insulin secretion from functional PanNETs prolonged survival, and anti-metastatic actions on aggressive PanNETs reduced the metastatic burden to less than before treatment." (PMID 35118189, 2022). "Adiponectin is a hormone that enhances insulin sensitivity and exerts antitumor function by binding its receptor on tumor cells." (PMID 36003786, 2022). "Within the insulin/IGF axis, IGF-1R is capable of stimulating the proliferation and migration of tumor cells through binding with insulin and IGF-1 and activating the downstream tumor-promoting signal pathways." (PMID 35296101, 2022). "In the two fly tumor models that produce ImpL2, insulin signaling is reduced in peripheral tissues and systemic organ wasting is observed." (PMID 35319749, 2022). "At present, he is still undergoing chemotherapy and maintains normal plasma glucose and insulin levels, and the residual tumor continues to shrink." (PMID 35865311, 2022). "These experiments demonstrate that cold exposure significantly decreases blood glucose levels and improves insulin sensitivity in tumour-bearing mice." (PMID 35922508, 2022). "This suggests that adding insulin undermines the efficacy of the SGLT2 inhibitor in slowing tumor growth." (PMID 35595952, 2022). "Ketogenic diet or exogenous supplements can induce ketosis, significantly reduce blood glucose and insulin, modulate tumor microenvironment, as well as slow down tumor progression and potential symptom burden." (PMID 36401321, 2022). "Next, we examined the correlations between PanIN plus tumor area and fasting insulin levels, glucose levels, and body weight in individual mice measured at 57 weeks of age, by pooled measurements (black) or within each group (colored)." (PMID 35189981, 2022). "Its impact is important on the factors that control tumor development, such as the immune system, inflammation, tissue perfusion, hypoxia, insulin resistance, metabolism, glucocorticoid levels, and cachexia." (PMID 36358820, 2022). "Treatment of RT2;B6 mice resulted in decreased viable tumor cell mass, lowered insulin secretion, and increased blood glucose." (PMID 35118189, 2022). "Tumor-derived miR-let7a induces an M2-like phenotype in macrophages by regulating the insulin/AKT/m-TOR signaling pathway, thereby enhancing tumor aggressiveness." (PMID 36362044, 2022). "These authors also showed that AspB10, an insulin analog that binds specifically to the IR, has a similar effect to increase tumor growth independently of IGF signaling." (PMID 35244142, 2022). "A low-carbohydrate diet also suppresses prostate cancer tumor growth in mice compared to a Western diet, which increases serum insulin, blood glucose, and tumor tissue insulin receptor levels." (PMID 35745105, 2022). "Employing chronic insulin infusion to prevent the effect of dapagliflozin to reduce plasma insulin concentrations, however, abrogated its effect to slow tumor growth in both lean and obese mice." (PMID 35595952, 2022).
tumor (continued). "In this same study, however, patients with high 18F-Fluorodeoxyglucose uptake on their PET scans received a mortality benefit from metformin, suggesting certain glucose-dependent but insulin-independent effects in the tumor microenvironment." (PMID 35244142, 2022). "Rare tumour INS expression indicated tumours would be responsive to pancreatic or therapeutic insulins." (PMID 34554347, 2022). "These reductions in plasma glucose and/or insulin concentrations inhibited tumor glucose uptake: chronic dapagliflozin treatment lowered MMTV-PyMT tumor [14C] 2-deoxyglucose uptake, more markedly than did acute treatment." (PMID 35595952, 2022). "While scientific rigor requires one to choose a target of interest and probe it as independently as possible, in vivo there is undoubtedly interplay between insulin and many other tumor-promoting or -limiting factors." (PMID 35244142, 2022). "For example, other than the role of glucose in supplying tumor proliferation with energy, its consumption also influences tumorigenesis by promoting the secretion of insulin, which is an oncogenic signaling factor." (PMID 35445073, 2022). "KEGG analysis revealed that the DE-MRGs mainly participated in tumor metabolism related pathways, including insulin metabolism and fatty acid metabolism." (PMID 36503378, 2022). "The Western diet directly promotes tumor cell proliferation via mechanisms involving the insulin/insulin-like growth factor 1 (IGF1)/phosphoinositide 3-kinase (PI3K) signaling pathway." (PMID 35745105, 2022). "The miR-375 gene is important for insulin secretion and glycogen synthase and acts as a tumor suppressor by downregulating numerous oncogenes, e.g. PDK1, JAK2, IGF1R, AEG-1, and suppressing the PI3K/Akt pathway." (PMID 35284957, 2022). "Next, we ascertained that metformin prevents a motile phenotype of BCAHC-1 cells triggered by the paracrine liaison between tumor cells and CAFs upon insulin activated CXCL12/CXCR4 axis." (PMID 35672854, 2022). "In untreated RT2;B6 mice from age 10 to 16 weeks, tumor size increased 3-fold, blood insulin increased to more than 2 ng/mL, glucose decreased to less than 30 mg/dL, and mortality reached 65%." (PMID 35118189, 2022). "In the adult ykiact and RasV12 scrib−/− tumor models, this hyperglycemia is largely due to the systemic reduction of insulin signaling by tumor-derived ImpL2, whereas in the RasV12 scrib−/− larval tumor model, it is a result of systemic autophagy." (PMID 35319749, 2022). "Apart from tumor regression and decreased tumor cell invasion, the glycemic index, urine ketone levels, serum insulin, and triglyceride levels were normalized, likely due to favorable modulation of the gut microbes." (PMID 35625485, 2022). "Elevated level of circulating CXCL10, as in tumour environment, can trigger β‐cell apoptosis resulting in significant reduction in insulin secretion." (PMID 34212132, 2021). "AMPK is not only a key regulator in cellular energy metabolism but also plays an essential regulatory role in many physiological processes such as inflammation, tumour growth and enhanced insulin sensitivity." (PMID 34676967, 2021). "An association between plasma insulin/IGF-1 concentrations and tumor development is widely acknowledged." (PMID 33802978, 2021). "We previously showed that advanced tumor disease reduced cardiac glucose uptake more than 60% and also affected insulin signaling." (PMID 34669013, 2021). "Our observations indicate that the main role of Wg in supporting the growth of yki3S/A tumors is to increase insulin/IGF signaling in a tumor-autonomous manner." (PMID 34078667, 2021). "The proteomic analysis of changes in the expression of 1,300 different proteins in the human EC cell line HEC-1A revealed that both metformin treatment and insulin supplementation led to anti-tumor as well as some tumor-promoting effects." (PMID 33690729, 2021).
tumor (continued). "Adenine was a key purine nucleobase in nucleic acids, and its derivatives regulated various physiological processes such as energy metabolism, tumor microenvironment, brain injury, and insulin secretion of β cells and adipogenesis." (PMID 35155569, 2021). "In the current study, we discovered that insulin promoted CRC deterioration in vitro and in vivo, particularly, with the presence of OA, insulin showed a more powerful tumor-promoting effect." (PMID 34434893, 2021). "The clonal distribution indicates that different parts of a tumour show different transcriptional activation leading to different INS and INS-IGF2 expression and corresponding polypeptide synthesis." (PMID 34170845, 2021). "Taking into account that insulin is discussed as being a growth factor in neoplasia, the KD appears to be the most effective strategy to attenuate insulin-mediated growth stimuli to tumor cells." (PMID 33806775, 2021). "Omentin-1, which has anti-inflammatory, insulin sensitizing, and tumor suppressive properties, is produced primarily by VAT and its secretion is increased with exercise training." (PMID 34638355, 2021). "The prognostic role of the insulin/IGF pathway has also been investigated on circulating tumor cells (CTCs) in BC patients." (PMID 33477996, 2021). "Our results demonstrate that mice bearing tumors fed with a Western diet presented bigger tumor mass with increased insulin sensitivity in these tissues." (PMID 34162829, 2021). "Various mechanisms such as altering hormones (androgen, IGF-1, insulin, circulating, and leptin) reduced tumor volume, and reformed antioxidative defense and immune care." (PMID 33927639, 2021). "The baseline covariates included in the first model were as follows: treatment received, PD at baseline, previous therapy, sex, BMI, hepatic tumor load, primary tumor type, tumor grade, chromogranin A levels, DM, metformin use, and insulin use." (PMID 35008233, 2021). "We now confirm their finding in a larger study, where 16 of 20 tumours stained positively for insulin." (PMID 34170845, 2021). "Adiponectin can influence carcinogenesis either through a direct action on the tumor cells via adiponectin receptors and their expression on tumor cells or through insulin-sensitizing effects." (PMID 33799622, 2021). "Several researchers using the same technique have reported that insulin sensitivity had been restored after surgical tumor resection." (PMID 34706697, 2021). "For example, gonadal hormone, growth hormone, thyroid hormone, insulin, etc., can increase the proportion of tumor cells in S phase and play a role in chemosensitizing of the tumor." (PMID 34203270, 2021). "Our study demonstrated that TRF effectively reduced insulin levels, improved insulin sensitivity and slowed tumor growth." (PMID 33495474, 2021). "Our results revealed an unprecedented role of Vav1 in sustaining the ATRA mediated differentiation of normal and tumor cells to insulin producing cells." (PMID 33165749, 2021). "The evidence for insulin production in these tumours is, for some of them, limited to staining with anti-insulin antibodies." (PMID 34170845, 2021). "Most tumours also display heterogeneous expression of polypeptides immunoreactive to monoclonal anti-insulin antibodies." (PMID 34170845, 2021). "Accordingly, fatty acid inhibition by etomoxir or lipolysis inhibition by nicotinic acid largely restored insulin sensitivity and glucose intolerance in tumor-bearing mice." (PMID 33801684, 2021).